MMP2 (matrix metallopeptidase 2)
Diseases named in the same sentence as MMP2 in open-access papers (continued):
Sharing a sentence is not in itself a finding about the gene and the disease.
Hypertension (continued). "The role of circulating MMP-2 and MMP-9 in the etiopathogenesis of essential hypertension has not yet been studied in connection with age." (PMID 33023122, 2020). "In VSMCs, CRID3 inhibited collagen synthesis induced by Ang II and CRID3 prevented the increased expression of MMP2 and MMP9 unlike TIMP2, indicating that suppressing NLRP3 inflammasome was a target in aortic fibrosis in hypertension." (PMID 30906225, 2019). "In addition, with aging, the activity of MMP-2 increases with the decrease in the quantity and functionality of elastic fibers (elastin) and the increase in the collagen content in the aortic artery, which is another factor that can lead to hypertension in the absence of estrogen hormones." (PMID 30133537, 2018).
Stroke (107 papers, 2009 to 2025). Sudden impairment of blood flow to a part of the brain due to occlusion or rupture of an artery to the brain. "MMP-2 has been considered as the “first responder” MMP post-stroke, and MMP-2 caused reversible BBB disruption." (PMID 39273389, 2024). "DNA methylation is also a co-factor that can increase the risk of stroke, as lower levels of MMP-2 methylation have been found in ischemic stroke patients compared to the control group, especially in males." (PMID 34445740, 2021). "In our study, we found that MMP-9 expression is significantly induced, whereas MMP-2 induction is relatively limited in stroke-susceptible haplogroup F cybrids in comparison with B cybrids." (PMID 32796743, 2020). "Several MMPs including MMP-2, -3, -7, -9, -10, and -1 have also been shown to be involved in causing one of the most fatal diseases in the CNS: stroke." (PMID 32466129, 2020). "The initial BBB breakdown occurs within 2–3 h of stroke onset, is associated with activation of MMP-2, and is accompanied by the development of vasogenic oedema (i.e., excess accumulation of fluid in the brain extracellular spaces)." (PMID 31281252, 2019). "Disruption of the blood-brain barrier following stroke is commonly associated with the action of two matrix metalloproteinases, MMP-2 and MMP-9." (PMID 24579051, 2014). "In the present study we show that MMP-2 gene variants are strongly associated with patient's functional disability at three months after stroke onset, in a large Portuguese population sample." (PMID 20222942, 2010). "The results presented strongly indicate that MMP-2 genetic variants are an important mediator of functional outcome after stroke." (PMID 20222942, 2010). "In patients with severe stroke both MMP-2 and MMP-9 have a strong association with edema formation and midline shift." (PMID 21110846, 2010). "Six SNPs in the MMP-2 gene were significantly associated with stroke outcome (0.0018<P < 0.0415), two of which survived the Bonferroni correction for multiple testing." (PMID 20222942, 2010). "Clinical studies conducted in patients with various types of stroke have revealed that MMP-2 gene is associated with the development of lacunar stroke." (PMID 21110846, 2010). "All but one MMP-2 gene variants associated with stroke in the overall population sample remained associated with ischemic stroke in this smaller subset." (PMID 20222942, 2010). "Genotype frequency distribution and association with stroke outcome at three months for MMP-2 SNPs." (PMID 20222942, 2010). "In the ischemic stroke sample, five out of the previously associated SNPs in the MMP-2 gene remained significantly associated with stroke outcome at three months under a log-additive model (0.0042<P < 0.0306), after adjusting for the same significant covariates (excluding type of stroke)." (PMID 20222942, 2010). "Haplotype frequency distribution of the MMP-2 and -9 genes, and association with stroke outcome." (PMID 20222942, 2010). "We show that SARS‐CoV2 infections drive a VWF/ADAMTS13 axis imbalance, inducing an increase in tPA while decreasing FIX, MMP‐2, and sICAM‐1 post‐stroke." (PMID 39972966, 2025). "For the SARS‐CoV2 positive IS cohort, MMP‐2 and sICAM‐1 returned to levels similar to the non‐stroke control cohort." (PMID 39972966, 2025). "Similar to CHD and HF, higher concentrations of GDF15 and IL6, along with TNFR1, Eotaxin, MMP1, and MMP2, conferred the highest HRs for incident stroke." (PMID 39695064, 2025). "Human serum studies have previously highlighted that MMP‐2 is unchanged in the acute phase post‐stroke." (PMID 39972966, 2025). "For instance, upregulation of αvβ3 levels post-stroke induces the internalization of important tight junction proteins occludin and zonula occludens (ZO-1) in ECs and promotes the secretion of MMP-2 and MMP-9." (PMID 39000490, 2024).
Stroke (continued). "There was a significant increase in MMP-2 expression in the stroke hemisphere of the r-tPA-treated mice (2 h of ischemia, but not 1 or 4 h) when compared with the control mice (p < 0.0001)." (PMID 39273389, 2024). "The aim of this study was to measure the levels of the inflammatory markers MMP-2 and -9 post-stroke in the brain and plasma of female and male offspring from mothers deficient in dietary folic acid or choline during pregnancy and lactation." (PMID 39273042, 2024). "It is reported that mice with reduced production of MMP-9 (a type of gelatinase MMP, along with MMP-2) following stroke presented with less cerebral injury compared to control mice." (PMID 39273042, 2024). "In rodent MCAO models, plasma activity of MMP‐9 and MMP‐2 is increased within 3 to 8 hours of stroke onset." (PMID 38379112, 2024). "An early rise within 2 hours after stroke of active MMP‐2 degrades type IV collagen and laminin in the vascular basement membrane and leads to the degradation of type IV collagen and laminin in the vascular basement membrane." (PMID 38379112, 2024). "In the long term, MMP-2 activity increases after stroke and remains elevated over a long period of time (months and years), as proven by the results in humans." (PMID 37511788, 2023). "To investigate the effect of inhibiting IL-10 expression on BBB integrity after PT stroke, we detected changes in MMP2 and MMP9 by RT-qPCR and their activity by gelatin zymography." (PMID 37196130, 2023). "If the HT is considered as delayed (occurs after 18–24h of stroke onset) apart from MMP-2 and MMP-9, MMP-3 as well as endogenous tPA, are involved." (PMID 36835040, 2023). "On the other hand, MMP-9 and MMP-2 inhibitors are able to antagonize the BBB damage in the experimental stroke model with fibrin-rich clot used to MCAO." (PMID 36835040, 2023). "MMP-2 was involved in the process of stroke injury in the early stage, and its activity and protein expression were obviously increased at this time." (PMID 35959401, 2022). "VEGF interacting with MMP2 regulated neovascular remodeling and neuroprotection after stroke injury." (PMID 35959401, 2022). "In stroke, biphasic BBB breakdown is caused by activated matrix metalloproteinase (MMP)-2, MMP-3 and MMP-9." (PMID 36224611, 2022). "Our finding indicated that baseline serum CRP, GDNF, IFN-γ, IGFBP-6, IL-4, LYVE-1, MMP-2, PAI-1, and PDGF-AA levels were associated with post-thrombolytic sICH in stroke." (PMID 35173671, 2022). "Upregulated MMP-9 and MMP-2 after stroke degrade TJs, such as occludin and Claudin-5, and microvascular basal lamina." (PMID 34483842, 2021). "One prospective study found that increased circulating levels of MMP-2 were independent predictors of myocardial infarction, stroke, peripheral embolization, and death among patients with AF." (PMID 34521347, 2021). "Following stroke, the levels of MMP-2 and MMP-9 are elevated in ischemic tissue and they contribute to BBB disruption." (PMID 34299322, 2021). "In mice with hyperhomocysteinemia (HHcy), a vascular dysfunction and stroke-like condition, the protein levels of MMP-2 and MMP-9 were significantly higher than that of the control mice." (PMID 32466129, 2020). "In stroke, MMP-2 and MMP-9 are considered the two most critical enzymes, and therefore, they were among the ones most studied." (PMID 32466129, 2020). "Several studies have showed that MMPs, particularly MMP2, is upregulated after stroke, cerebral hypoxia/ischemia, and TBI28–30." (PMID 33014432, 2020). "In a HBOT preconditioning model, it was shown that hyperbaric environment leads to a decrement of MMP-2 and 9 in an animal stroke model." (PMID 31801203, 2019). "The BBB permeability due to hyperglycemia during early reperfusion in stroke is involved in autophagy- and MMP-2/9-mediated reduction and redistribution of tight junction proteins." (PMID 31811815, 2019).
Stroke (continued). "In the pathological progression of stroke, gelatinases including MMP-2 and MMP-9, possess the ability to activate numerous pro-inflammatory agents, including chemokine CXCL-8, interleukin 1β, and tumor necrosis factor α." (PMID 30953513, 2019). "It has been shown previously that the levels of MMP-2 are lower in the acute phase of stroke mice model." (PMID 30131754, 2018). "IL-18 is also present in the area of liquefactive necrosis for at least eight weeks following stroke, and there are also strikingly high levels of MMP-2, MMP-3, and MMP-8." (PMID 30417081, 2018). "Results from the present study showed that the increment of plasma MMP-9 and brain MMP-2 activity after stroke were significantly inhibited by the combination of DHI with t-PA." (PMID 29681849, 2018). "Our results in stroke patients highlight a remarkable presence of tPA, MMP-2, and MMP-9 activities in peri-infarct zones and most importantly in regions remote from the infarct." (PMID 28290150, 2018). "After stroke, significant increasement of the MMP-2 protein and reduction of the occluding protein were found in vehicle group." (PMID 29681849, 2018). "During stroke, MMP-2 and MMP-9 are up-regulated, leading to increased BBB permeability through degradation of endothelial matrix proteins." (PMID 25914628, 2015). "The MMP-9 activity was markedly increased from days 2 to 14 after stroke, whereas a significantly smaller increase in MMP-2 activity was observed compared with MMP-9 activity." (PMID 26581247, 2015). "MMP-2 is constitutively expressed at low levels in normal brain tissue; however stroke increases its expression and activity and also induces the expression of MMP-9." (PMID 24579051, 2014). "In support of these data, a clinical study reported an increase in plasma MMP-2 only in patients with lacunar (mild) stroke early (within 12 h) and this was related to better outcome." (PMID 23565108, 2013). "Exercise therapy improves long-term stroke outcome by MMP2-VEGF-dependent mechanisms related to improved cerebral blood flow." (PMID 23598418, 2013). "We first focused on interrelations between the ischemia-induced changes in BBB permeability, MMP-2 and -9 in controls to explore the natural pathophysiology in the applied model of experimental stroke." (PMID 22273146, 2012). "Other authors noted that MMP-9 responses in the acute phase, and afterwards MMP-2 in later phases after stroke." (PMID 21679435, 2011). "In the present study we tested the impact of genetic variants in MMP-2 and MMP-9 in stroke recovery, in a population sample of 546 patients evaluated for stroke outcome at three months after the stroke event." (PMID 20222942, 2010). "In the present study, the role of MMP-2 and MMP-9 genetic variants in stroke recovery was investigated in 546 stroke patients." (PMID 20222942, 2010). "Different MMPs are expressed in different conditions and at different times following stroke, with MMP-2 being amongst the first activated, followed by MMP-9 in later stages of inflammation and repair." (PMID 21110846, 2010). "The association results after multiple testing correction, using the stringent Bonferroni method or the SNPSpD approach, strongly support a role for MMP-2 in stroke recovery." (PMID 20222942, 2010). "In rodent models, MMP-9 responses appear to dominate in the acute phase, whereas MMP-2 elevations seem to occur in the delayed phase, days after stroke." (PMID 20514206, 2009). "Immunohistochemistry demonstrated strong staining of MMP-2, HGF-alpha, MCP-1 and Tie-2 in stroke-associated regions of active remodeling in association with CD105 positive staining." (PMID 19292924, 2009). "Neutralization of IL-1β after experimental stroke significantly reduced MMP2/9 activity in CCA plaques 7 days after stroke and increased fibrous cap thickness compared with control (isotype IgG) treatment, indicating a causative role of IL-1β in mediating inflammatory plaque degradation." (PMID 39112714, 2024).
Stroke (continued). "Transient inhibition of MMP2/9 after stroke rescues the plasticity of the damaged cortex." (PMID 36959823, 2023). "Stroke patients have a significantly higher serum level of MMP-2 and MMP-9 than healthy controls." (PMID 35477576, 2022). "MMP2 can also promote endogenous repair, especially angiogenesis, cerebral blood flow reconstruction and repair of brain tissue damage in the recovery stage after stroke." (PMID 35959401, 2022). "In general, MMP2 is an important regulatory indicator of stroke occurrence and recovery." (PMID 35959401, 2022). "The most significantly upregulated genes, including Lpl, Spp1, Cd36, Mmp2, and Mmp19, and the most highly enriched genes, including Cd5l, Mmp3, Mmp12, and Mmp13, indicate a pronounced disturbance in lipid homeostasis in infarcts at 7 weeks after stroke." (PMID 34819339, 2022). "No sex differences were reported for plasma levels of tissue inhibitor metalloproteinase 1 (TIMP-1) and insulin-like growth factor 1 (IGF-1) 1 day after stroke, matrix metalloproteinase 2 (MMP2) within 2 days after stroke, and matrix metalloproteinase 9 (MMP9) 2 days and 1 month after stroke." (PMID 34858141, 2021). "Plasma MMP-2 levels have been found to be associated with stroke outcome; however, MMP-2 concentration is inversely associated with the atherothrombotic subtype of stroke." (PMID 33153204, 2020). "Additionally, some molecules are highly expressed in the stroke microenvironment, such as matrix metalloproteinase-2 (MMP-2) and G-protein coupled chemokine receptor-4 (CXCR4)." (PMID 33241704, 2020). "Previous reports showed that MMP-2 deficiency in experimental stroke and serum MMP-2 levels in stroke patients did not affect ischemic lesion size or stroke severity, respectively." (PMID 28936196, 2017). "The accumulating data revealed that MMPs are deleterious in stroke, in particular MMP-2 and MMP-9." (PMID 28912713, 2017). "MMP-2, MMP-3, MMP-9, MMP-13, and MT1-MMP have all been identified in neuronal nuclei and gelatinases (MMP-2 and MMP-9) and MMP-3 have been implicated in the progression of infarct volume and neuronal death in animal models of stroke and ischemic stroke patients." (PMID 26925194, 2016). "Furthermore, in an OGD model of stroke with primary rat cortical neurons, increased intranuclear location of gelatinase activity and elevated levels of both MMP-2 and MMP-9 of nuclear extracts are detected." (PMID 26925194, 2016). "Interestingly, at this relative late reperfusion time points (24 hrs after stroke onset), MMP-2 appeared to be constitutively expressed at much lower levels compared with MMP-9, and was not affected by ischemia and reperfusion." (PMID 22146586, 2011). "Shortly after stroke, MMP-2 and MMP-9 have mainly damaging effects for brain tissue." (PMID 20222942, 2010). "The present study further reinforces the contribution of MMPs for stroke recovery by showing that specific MMP-2, but not MMP-9, gene variants influence stroke outcome." (PMID 20222942, 2010). "At present, we cannot dissect whether gene variation in MMP-2 is more important for the damaging effects in the earlier stages after stroke, or to the beneficial delayed responses, or both." (PMID 20222942, 2010). "On one hand it challenges the usefulness of MMP inhibitors for the treatment of stroke, not only because the time window of usefulness is likely limited, but also because it may depend on the individual's MMP-2 genotype." (PMID 20222942, 2010). "Together with previous observations, the study leads to the hypothesis that individual variation in the MMP-2 gene may influence stroke treatment outcome." (PMID 20222942, 2010). "Here, we also showed that HBMEC exposed to OGD demonstrated up-regulated HIF-1α and Hsp70 concomitant with MCP-1/MMP-2 and Tie-2 gene and protein expression suggesting at least some of the proteins may be produced by EC de novo after stroke." (PMID 19292924, 2009).